RAD51 (RAD51 recombinase)
Diseases named in the same sentence as RAD51 in open-access papers (continued):
Sharing a sentence is not in itself a finding about the gene and the disease.
Bloom syndrome (2 papers, 2014 to 2021). Bloom syndrome (BSyn) is a rare chromosomal breakage syndrome characterized by a marked genetic instability associated with pre- and postnatal growth retardation, facial sun-sensitive telangiectatic erythema, increased susceptibility to infections, and predisposition to cancer. "Our results showed that SQ and SCLC had overexpressed genes throughout the pathway with 10 of 11 genes overexpressed including the very important BRCA2, RAD51 paralogs and BLM (Bloom syndrome mutated)." (PMID 25325012, 2014). "BLM can displace the invading strand from the D-loop and thus can disrupt the RAD51–ssDNA filaments, which explains why BLM has also been termed an “anti-recombination” protein, which is a feature observed in Bloom syndrome (BS) patient cells." (PMID 33718381, 2021).
bone cancer (2 papers, 2019 to 2020). A primary or metastatic malignant neoplasm affecting the bone or articular cartilage. "We report here the generation of viable individual knockouts of the five classical RAD51 paralogs in two different transformed human cell lines: U2OS cells of bone cancer origin and HEK293 cells that exhibit cancer stem cell features." (PMID 31584931, 2019).
chondrosarcoma (2 papers, 2019 to 2021). A malignant cartilaginous matrix-producing mesenchymal neoplasm arising from the bone and soft tissue. "After a 2 h recovery of γ-radiation treatment, chondrosarcoma cell lines showed a significant induction of RAD51 foci, indicative of a proficient homologous recombination pathway." (PMID 34916568, 2021). "A RAD51 foci assay shows that CH2879 and SW1353 cells have a functioning homologous recombination pathway, indicating that PARP inhibitor sensitivity in chondrosarcoma partly depends on a different mechanism than classical homologous recombination pathway defects, such as BRCA mutations." (PMID 31810230, 2019).
colorectal tumor (2 papers, 2023 to 2024). "MiR-506 was also involved in the chemo-response of ovarian and colorectal tumors via RAD51 and PPARα, respectively." (PMID 37051101, 2023). "This is based upon the detection of basal pSer33-RPA32 levels, RAD51 foci, ATM, and RAD51C expression in formalin-fixed paraffin-embedded colorectal tumor samples or derived preclinical models." (PMID 39456536, 2024).
diabetes (2 papers, 2014 to 2024). "The upregulation of CD73 with agents, including AGT-5, Aire-overexpressing DCs, Aspirin, BAFFR-Fc, CD4+ peptide, ICAs, IL-2 therapies, SAgAs, sCD73, stem cells, RAD51 inhibitor, TLR9 inhibitor, and VD, decreased diabetes and atherosclerosis development." (PMID 39735551, 2024). "Overexpressing CD73 with agents, such as AGT-5, Aire-overexpressing DCs, BAFFR-Fc, CD4+ peptide, ICAs, IL-2 therapies, SAgAs, sCD73, RAD51 inhibitor, TLR9 inhibitor, and VD decreases diabetes development." (PMID 39735551, 2024). "The upregulation of CD73 with agents, including AGT-5, Aire-overexpressing DCs, Aspirin, BAFFR-Fc, CD4+ peptide, ICAs, IL-2 therapies, SAgAs, sCD73, stem cells, RAD51 inhibitor, TLR9 inhibitor, and VD, decreased the development of diabetes and atherosclerosis in preclinical trials." (PMID 39735551, 2024). "Suppressing RAD51 with CRISPR/cas9 and inhibitors (such as 4,4’-diisothiocyanatostilbene-2, 2’-disulfonic acid) decreases the diabetes process by reducing diabetogenic T cell responses via expanding CD73+ B lymphocytes that exert regulatory activity in T1DM-susceptible nonobese diabetic (NOD) mice." (PMID 39735551, 2024).
endometriosis (2 papers, 2018 to 2024). The growth of functional endometrial tissue in anatomic sites outside the uterine body. "Understanding the intersection of mutations found in the RAD51 regulators in POI, endometriosis and PCOS will likely illuminate mechanisms that affect molecular medicine." (PMID 39359934, 2024). "Endometrial expression of BRCA1 and Rad51 mRNA proved significantly lower in the endometriosis group (vs. controls), as did ovarian expression of BRCA1 and BRCA2 mRNA." (PMID 30622513, 2018). "Mutations in the RAD51 modulators are particularly well-documented in reproductive cancers and therefore they likely play a direct role in the development of reproductive disorders like POI, endometriosis, and PCOS." (PMID 39359934, 2024). "Regulators of RAD51 play important roles in maintaining genome integrity and variations in these genes have been identified in female reproductive diseases including primary ovarian insufficiency (POI), endometriosis, and polycystic ovary syndrome (PCOS)." (PMID 39359934, 2024). "Of the three reproductive disorders we examined, POI has the largest dataset on RAD51 modulators, while endometriosis and PCOS are severely lacking." (PMID 39359934, 2024). "Indeed, expression levels of BRCA1, Rad51, and ATM in endometrial tissue proved to be lower in the endometriosis group than in control subjects, as were expression levels of BRCA1 and BRCA2 in ovarian tissue." (PMID 30622513, 2018).
esophageal adenocarcinoma (2 papers, 2020 to 2022). A malignant tumor with glandular differentiation arising predominantly from Barrett mucosa in the lower third of the esophagus. "Based on these observations, we investigated if RAD51 expression correlates with immune components involved in inflammation and/or immune surveillance in esophageal adenocarcinoma (GSE13898)." (PMID 36428789, 2022). "Breast (MCF7), colon (HCT116) and esophageal adenocarcinoma (OE19) cell lines treated with RAD51 inhibitor, CPT or combination for 48 h were also evaluated for apoptosis using flow cytometry." (PMID 36428789, 2022). "Esophageal adenocarcinoma (OE19, FLO-1), colon (HCT116) and breast (MCF7) cancer cell lines were treated with RAD51 inhibitor (RI-1), camptothecin (CPT) or combination of both for 48 h and cell viability assessed as described in Methods." (PMID 36428789, 2022).
gastric tumor (2 papers, 2016 to 2023). "Previous studies of colon and gastric tumor lines and of xenographic models have also observed that the level of expression of the RAD51 protein is drastically reduced after treatment with PCI-24781, leading to inhibition of DSB repair by homologous recombination." (PMID 27095947, 2016). "In addition, gastric tumor cells exhibited evident DNA damage and DNA repair defect, supported by downregulation of well-known genes involved in DNA damage and repair response, including RAD51, BRAC1, BRCA2 and BARD1." (PMID 36755269, 2023).
heart failure (2 papers, 2022 to 2024). Inability of the heart to pump blood at an adequate rate to meet tissue metabolic requirements. "RAD51 polymorphisms were associated with symptoms of heart failure according to NYHA class and the occurrence of a new primary tumor, while XRCC3 polymorphisms were associated with tumor differentiation and skin adverse events according to LENT-SOMA criteria." (PMID 36139526, 2022). "In our study, carriers of RAD51 rs1801321 TT genotype more often had higher NYHA class, while carriers of RAD51 rs12593359 GG genotype were less likely to exhibit symptoms of heart failure in both single SNP and haplotype analysis." (PMID 36139526, 2022).
inflammatory bowel disease (2 papers, 2022). A spectrum of small and large bowel inflammatory diseases of unknown etiology. "In inflammatory bowel disease (IBD), miR-23a and miR-155 enhance the deleterious effects of neutrophils by targeting lamin B1 and RAD51 (a homologous recombination regulator), inhibiting tissue healing responses." (PMID 35634335, 2022).
malignant mesothelioma (2 papers, 2019 to 2025). A malignant neoplasm of the pleura or peritoneum, arising from mesothelial cells. "The loss-of-expression of RAD51 is not surprising, as it is commonly deleted in malignant mesothelioma due to frequent losses from 15q11.1–22." (PMID 30700254, 2019).
metastatic melanoma (2 papers, 2020 to 2023). A melanoma that has spread from its primary site to another anatomic site. "Among them, CDKN1A, CDKN2A, CXCR4 and RAD51 were significantly down-regulated in metastatic melanoma when compared with the primary type." (PMID 38070141, 2023). "We found that metastatic melanoma cells are susceptible to inhibition of Rad51, while the viability of non-cancerous skin cells was not affected by treatment with Rad51i." (PMID 32719412, 2020).
oligodendroglioma (2 papers, 2016 to 2021). A well-differentiated (WHO grade II), diffusely infiltrating neuroglial tumor, typically located in the cerebral hemispheres. "In addition, in a mouse model of PDGF-induced oligodendrogliomas, p27Kip1 deficiency was shown to increase the occurrence of chromatid breaks and reduce the formation of Rad51 repair foci in response to IR." (PMID 27611996, 2016).
ovarian dysgenesis (2 papers, 2015 to 2022). "Missense variants and single-nucleotide polymorphisms in RAD51 have been associated with human ovarian dysgenesis and with lower age of menopause, respectively." (PMID 34402903, 2022). "Importantly, mutations introduced into these Hop2 and Mnd1 domains, including the HOP2 p.del201Glu mutation present in a patient of XX ovarian dysgenesis, diminish the association and functional synergy of Hop2-Mnd1 with both RAD51 and DMC1." (PMID 25820426, 2015).
Premature ovarian insufficiency (2 papers, 2022 to 2025). Amenorrhea due to loss of ovarian function before the age of 40. "Recent studies identifying factors responsible for primary and premature ovarian insufficiency (POI) have reported either dramatic downregulation or non-functional variants of several DDR pathway members, such as BRCA1, RAD51, ATR, MSH4, MSH5, and FANC genes." (PMID 40148269, 2025).
pulmonary arterial hypertension (2 papers, 2018 to 2024). Pulmonary arterial hypertension (PAH) is a group of diseases characterized by mean pulmonary artery pressure >20 mmHg and elevated pulmonary arterial resistance leading to right heart failure. "Loss of RAD51, which causes DNA damage and cell death, is also detected in animal models and human patients with pulmonary arterial hypertension." (PMID 30272025, 2018). "Our findings pointing to a molecular link between BMP9 signaling and RAD51 open a new therapeutic avenue aimed at rescuing the DNA repair enzyme and preventing DNA damage as a way to halt or delay the development of vascular remodeling in pulmonary arterial hypertension from an early stage." (PMID 30272025, 2018). "Finally, we examined whether attenuation of RAD51 could be observed in a non-genetic model of pulmonary arterial hypertension, the Sugen–Hypoxia38-treated rats, and in human patients affected by idiopathic pulmonary arterial hypertension." (PMID 30272025, 2018).
radiation pneumonitis (2 papers, 2011 to 2022). Inflammation of the lung due to harmful effects of ionizing or non-ionizing radiation. "In summary, we found that HR genetic polymorphisms, particularly RAD51 −135G>C, may influence the overall survival and risk of radiation pneumonitis in NSCLC patients treated with definitive radio(chemo)therapy." (PMID 21647442, 2011). "Our study suggests that HR genetic polymorphisms, particularly RAD51 −135G>C, may influence overall survival and radiation pneumonitis in NSCLC patients treated with definitive radio(chemo)therapy." (PMID 21647442, 2011).
rheumatoid arthritis (2 papers, 2018 to 2024). A chronic, systemic autoimmune disorder characterized by inflammation in the synovial membranes and articular surfaces. "We saw an increase in expression of 3 DDRFs including Rad51 (Rheumatoid arthritis), XRCC4 (lesional skin), and BRCA2 (asthma) while 1DDRFs was downregulated." (PMID 29867559, 2018). "Polymorphisms of homologous recombination RAD51 were found to be associated with cancer and rheumatoid arthritis, but never before in mood disorders." (PMID 38555957, 2024).
skin cutaneous melanoma (2 papers, 2021 to 2025). "Many of them were previously appreciated in the genome of skin melanomas (e.g., MITF, NOTCH2, PD-L1 and JAK2 amplifications, or CDKN2A deletions); however, the CNAs in genomic locations harboring PAX5, ETS1, BCL7, RAD51, APAF1, FOXO3 and CTNNA1 are novel." (PMID 33779796, 2021).
sterility (2 papers, 2019 to 2022). "Conditional disruption of RAD51 in germ cells by Vasa-Cre led to sterility due to complete germ cell loss." (PMID 35292640, 2022). "While Meilb2 KO male mice showed almost complete loss of RAD51 and DMC1 localizations leading to complete sterility, the female KO mice showed a reduction by almost half in the localization of these recombinases leading to subfertility (a 40% reduction in litter size)." (PMID 30760716, 2019). "We show here that MEILB2 is a master regulator of meiotic recombinases and the localization of RAD51 and DMC1 at meiotic DSBs is completely abolished in Meilb2 KO male mice, leading to errors in meiotic DSB repair and subsequent sterility." (PMID 30760716, 2019).
stomach adenocarcinoma (2 papers, 2022 to 2025). "In stomach adenocarcinoma (STAD), KIF4A is co-upregulated with HRR genes like RAD51, exacerbating genomic instability." (PMID 41361459, 2025).
Telangiectasia (2 papers, 2015 to 2024). Telangiectasias refer to small dilated blood vessels located near the surface of the skin or mucous membranes, measuring between 0.5 and 1 millimeter in diameter. "Therefore, next we investigated the status of a few key DNA repair proteins: pATM, pATR (ataxia telangiectasia and Rad3-related), and RAD51 in the parental and radioresistant AC cells after gamma-irradiation with dose of 5 Gy." (PMID 26517240, 2015).
thymoma (2 papers, 2022 to 2025). A neoplasm arising from the epithelial cells of the thymus. "Most strikingly, in thymoma (THYM), most of the immune cell scores were strongly and positively associated with RAD51, but most of the stroma cell scores were strongly and negatively associated with RAD51." (PMID 35359409, 2022). "Results showed that RAD51 was significantly associated with worse overall survivals in 11 cancer types, while RAD51 was associated with better overall survivals in rectum adenocarcinoma (READ) and thymoma (THYM)." (PMID 35359409, 2022).
tongue squamous cell carcinoma (2 papers, 2020 to 2025). A squamous cell carcinoma that arises from the tongue. "We compared RAD51 expression in oral mucosa epithelial cells (OMECs), keratinocytes, and tongue squamous cell carcinoma cells (TSCCs) by Western blot analysis." (PMID 32190537, 2020). "Next, to further elucidate RAD51's functional roles, we employed the HSC‐3 cell line—representing an aggressive tongue squamous cell carcinoma subtype of OSCC with particularly poor prognosis and unique therapeutic challenges." (PMID 41350246, 2025).
uveal melanoma (2 papers, 2022 to 2025). A melanoma derived from melanocytes of the uveal tract. "Finally, RAD51's pan‐cancer progression‐free interval (PFI) analysis predicted poor prognosis in 10 cancers: OSCC, PRAD, LUAD, LGG, LIHC, KIRP, MESO, uveal melanoma (UVM), PAAD and PCPG, with statistical significance (p < 0.05)." (PMID 41350246, 2025).
Werner syndrome (2 papers, 2021 to 2022). "In this regard, it will be interesting to know if RAD51 destabilization is a possible mechanism of type 1 IFN induction in Werner syndrome." (PMID 34381458, 2021).
angiosarcoma (1 paper, 2023). A malignant tumor arising from the endothelial cells of the blood vessels. "EME1, FANCA, RAD51, TP53BP1, RAD51C, RPA1, and XRCC2 exhibited alterations in more than half the cases of the angiosarcoma cohort." (PMID 36779660, 2023).
ataxia telangiectasia (1 paper, 2024). Ataxia-telangiectasia is the association of severe combined immunodeficiency (affecting mainly the humoral immune response) with progressive cerebellar ataxia. "For example, overexpression of SIRT6 instead of Rad51 or NBS1 rescues HR repair in ageing cells, and restoration of the NAD+/SIRT1 pathway improves healthspan in Ataxia-telangiectasia models via mitophagy and DNA repair." (PMID 39394181, 2024).
autoimmune disease (1 paper, 2019). A disorder resulting from loss of function or tissue destruction of an organ or multiple organs, arising from humoral or cellular immune responses of the individual to their own tissue constituents. "They investigated a characteristic autoantibody (3E10) from the autoimmune disease systemic lupus erythematosus, and found that it possesses dual specificity to bind RAD51 in addition to its well-known binding of DNA79." (PMID 31375703, 2019).
basal ganglia disorder (1 paper, 2015). A disease involving the basal ganglia. "Mirror movements are usually seen in early childhood due to mutations in the DCC and RAD51 genes, although they may sometimes also occur in patients with basal ganglia disorders and strokes, mainly of the corona radiata." (PMID 26528234, 2015).
bladder tumors (1 paper, 2018). "To check whether this assay can be used to determine the effectivity of heat-induced HR-deficiency in bladder tumors, we first studied the appearance of RAD51-foci in the T24 and RT112 cell lines." (PMID 30550547, 2018). "In 64% of 37 analyzed primary bladder tumor samples, hyperthermia induced similar morphological changes in RAD51 foci." (PMID 30550547, 2018). "Next, we applied the RAD51 focus formation assay to 48 freshly isolated bladder tumor samples." (PMID 30550547, 2018). "The cytochrome C assay and the RAD51 focus formation assay are both feasible on freshly obtained bladder tumors, and could serve to predict the efficacy of hyperthermia together with cytotoxic agents, such as MMC or cisplatin." (PMID 30550547, 2018).
cardiomyopathy (1 paper, 2012). A disease of the heart muscle or myocardium proper. "In the myocardium, Dox-induced cardiomyopathy was associated with an increase in γH2AX expression and a reduction in Rad51 and MRE11 expression and increased apoptosis." (PMID 22384017, 2012).
Chagas disease (1 paper, 2018). A parasitic infection caused by Trypanosoma cruzi. "In Trypanosoma cruzi, the etiologic agent of Chagas disease, Rad51 (TcRad51) is a central enzyme for homologous recombination." (PMID 30422982, 2018).
chordoma (1 paper, 2021). Chordomas are rare malignant tumors arising from embryonic remnants of the notochord in axial skeleton. "Interestingly, the inhibition of RAD51 has been shown to sensitize chordoma cells to radiations in vitro." (PMID 33672032, 2021). "As our work shows that the inhibition of ALDH activity sensitizes cells to radiations, we wonder whether the inhibition of both RAD51 and ALDH could have synergistic effects and improved response to radiation in chordoma." (PMID 33672032, 2021).
chromophobe carcinoma (1 paper, 2016). "Consistently, we found the mRNA expression of Rad51 was significantly down-regulated in renal tumours (clear cell carcinoma, chromophobe carcinoma, papillary carcinoma and metastatic clear cell carcinoma) compared with human normal renal tissues." (PMID 27170370, 2016). "In comparison with control renal tissues, all classes of renal carcinoma, namely clear cell carcinoma, chromophobe carcinoma, papillary carcinoma and metastatic clear cell carcinoma, showed significantly decreased expression of Rad51 which plays a major role in maintaining genomic stability." (PMID 27170370, 2016).
clear cell renal cell carcinoma (1 paper, 2024). "Homologous recombination deficiency (HRD), though largely uncharacterized in clear cell renal cell carcinoma (ccRCC), was found associated with RAD51 loss of expression." (PMID 38607586, 2024).
colorectal adenoma (1 paper, 2020). An adenoma that arises from the colon or rectum. "Previously, studies related to RAD51 and XRCC2 genes polymorphisms have recognized association between the distribution of these polymorphisms and the vulnerability of colorectal adenoma or cancer." (PMID 32458654, 2020).